CLU (clusterin)
Diseases named in the same sentence as CLU in open-access papers (continued):
Sharing a sentence is not in itself a finding about the gene and the disease.
diabetes (37 papers, 2008 to 2025). "Called “clusterin”.Protects cells against damage from oxidation, inflammation, and apoptosis.Associated with atherosclerosis, obesity, and diabetes." (PMID 39940892, 2025). "Investigation concerning humans is restricted to single reports on the urinary clusterin in patients with diabetes mellitus and promising results of a diagnostic multi-biomarker kit including urine clusterin in the scope of indices of chronic kidney injury." (PMID 32796610, 2020). "Our results also revealed associations of higher plasma clusterin with diabetes, dyslipidemia, and higher hsCRP—markers which are known to increase AD risk." (PMID 29324756, 2018). "In addition, CLU is associated with lipid transport, apoptosis, tissue remodeling, stress response, inflammatory skin diseases, diabetes, and metabolic syndrome." (PMID 32602849, 2020). "For the same reason, elevated plasma clusterin may also represent a protective mechanism against cognitive impairment in response to oxidative stress that caused by longer diabetes duration." (PMID 27516739, 2016). "Previous studies suggest that during diabetes-induced retinal damage, cytoplasmic clusterin is likely to be associated with protection from cell death, while nuclear clusterin might promote cell death." (PMID 22390717, 2012). "Furthermore, the association between clusterin levels and diabetic complications may explain the mechanisms underlying diabetes-related pathologies." (PMID 39458076, 2024). "Moreover, clusterin appears to be an encouraging biomarker in the management of diabetic kidney disease as the urinary levels of clusterin are associated with the severity of diabetic nephropathy in patients with diabetes." (PMID 35722493, 2022). "CLU is an heterodimeric disulfide-linked protein of ~ 75–80 kDa involved in several physiological processes including lipid transportation in serum, cellular senescence, aging and various age-related diseases, like neurodegeneration, inflammation, vascular damage, diabetes and tumourigenesis." (PMID 30967152, 2019). "Further studies need to be conducted to determine whether clusterin can be used as an underlying early marker of diabetes-associated MCI; in addition, studies with a larger sample-size should be performed to investigate the association between rs11136000 polymorphism and MCI in T2DM." (PMID 27516739, 2016). "Plasma clusterin has been associated with diabetes mellitus, while polymorphisms of the CLU gene, the gene encoding clusterin, are linked to impaired insulin secretion and insulin resistance." (PMID 38396489, 2024). "Macrophage chemoattractant protein-1 (MCP-1), activin-A, and clusterin are chemokines with known roles in diabetes and obesity." (PMID 38396489, 2024). "Accordingly, we investigated the impact of metabolic alterations, including pre-existing obesity or diabetes, on clusterin concentrations in ICU patients." (PMID 36553017, 2022). "Studies on humans are limited to the one study on urinary clusterin in diabetes mellitus patients and the encouraging outcomes of the testing multi-biomarker kit containing urinary clusterin in the range of indicators of acute and chronic renal damage." (PMID 36648873, 2022). "CD99, CLU, CD14, and SAA2 have been reported to be associated with diabetes from human serum proteins." (PMID 33995275, 2021). "Taken together, our observations provide in vivo evidence which corroborate the notion that CLU is a potential modulator of metabolic and/or proteostatic pathways playing a significant functional role in diabetes and tumorigenesis." (PMID 33744871, 2021). "Our observations provide in vivo evidence corroborating the notion that CLU is a potential modulator of metabolic and/or proteostatic pathways playing an important role in diabetes and tumorigenesis." (PMID 33744871, 2021).
diabetes (continued). "First, CLU is ubiquitously expressed in most cells and tissues, and is upregulated under a variety of pathological conditions including ageing, diabetes, atherosclerosis and degenerative diseases." (PMID 34075162, 2021). "Plasma clusterin was significantly higher in women, blacks, current smokers, and in those with diabetes, dyslipidemia, and higher hsCRP." (PMID 29324756, 2018). "The expression of clusterin is increased in several diseases, including diabetes, atherosclerosis, and Alzheimer's disease." (PMID 29200898, 2017). "Another study has found a strong positive correlation between clusterin levels in HDL and insulin sensitivity which is important during pathology of diabetes-associated MCI." (PMID 27516739, 2016). "Multivariable regression revealed that educational attainment, duration of diabetes, and HDL-c and clusterin levels are associated with MCI in T2DM patients." (PMID 27516739, 2016). "Multivariable regression model showed that educational attainment, duration of diabetes, high-density lipoprotein cholesterol (HDL-c), and plasma clusterin levels are associated with MCI in T2DM patients." (PMID 27516739, 2016). "High clusterin level, low HDL-c concentration, long duration of diabetes, and low educational attainment are associated with MCI in T2DM patients." (PMID 27516739, 2016). "It is suggested that CLU gene is involved in many severe physiological disease such as diabetes and neuron degeneration." (PMID 27516739, 2016). "In our study, multivariable logistic regression model shows that educational attainment, duration of diabetes, low HDL-C, as well as clusterin are associated with MCI in diabetic patients." (PMID 27516739, 2016). "In addition, glomerular clusterin levels were found to be higher in 10 patients with diabetes compared to the control group." (PMID 38396489, 2024). "Importantly, seven factors, namely rheumatoid arthritis (RA), diabetes, depression, homocysteine, folic acid, clusterin in cerebrospinal fluid, and cognitive activity, exhibited remarkably significant effects at p < 10−6." (PMID 39044503, 2024). "An increase in clusterin levels among diabetic patients may show the impairment of the protective system against complications of diabetes, such as diabetic nephropathy and cardiovascular diseases." (PMID 39458076, 2024). "BRD7 suppressed Clusterin expression via modulating Clusterin promoter hypermethylation in an EZH2 dependent manner, thereby suppressing AMPK signaling to facilitate ferroptosis and induce diabetes-associated testicular damage." (PMID 38992588, 2024). "Clusterin levels are up-regulated under conditions of cell stress and tissue injury and in patients suffering from myocardial infarction, dialyses-related amyloidosis, atherosclerosis, cancer, diabetes and neurodegenerative diseases." (PMID 32605184, 2020). "Next, we investigated whether clusterin expression is altered in diabetes by measuring CLU mRNA in a human podocyte cell line under various diabetic conditions." (PMID 32913257, 2020). "However, we demonstrate that treating podocytes with methylglyoxal to mimic diabetes-related oxidative stress increased CLU mRNA expression." (PMID 32913257, 2020). "CLU is ubiquitously expressed in most cells and tissues, and is upregulated under a variety of pathological conditions including ageing, diabetes, atherosclerosis, degenerative diseases, moreover it has recently drawn much attention because of its association with cancer promotion and metastasis." (PMID 26076476, 2015). "The role of Clusterin in attenuation of inflammation and reverse cholesterol transfer makes this molecule a potential candidate as a marker for cancer, cardiovascular disease, diabetes mellitus, and metabolic syndrome." (PMID 26076476, 2015). "The role of clusterin in attenuation of inflammation and reverse cholesterol transfer makes this molecule a potential candidate as a marker for cancer, cardiovascular diseases, diabetes mellitus, and metabolic syndrome." (PMID 26076476, 2015).
diabetes (continued). "However, the elevation of clusterin in diabetes has been challenged, as it disappeared after adjusting for the level of glycemia." (PMID 24949022, 2014). "Independently of diabetes, glypican 4, clusterin, chemerin and progranulin are related with parameters of insulin sensitivity, suggesting that these adipokines may play a role in the development of insulin resistance." (PMID 24968098, 2014). "Therefore, CLU may be a promising therapeutic target for macrophage inflammation and atherosclerosis induced by diabetes." (PMID 40337510, 2025). "The multifunctional glycoprotein clusterin has been involved in lipid metabolism, apoptosis, and inflammation and, because of its roles in cellular stress response and tissue remodeling, also in the development of diabetes complications affecting both microvessels and macrovessels." (PMID 39458076, 2024). "Our results indicate that the increase in clusterin concentration immediately after AMI might be strongly associated to myocardial necrosis and not be caused by any underlying factors such as atherosclerosis and diabetes." (PMID 32605184, 2020). "Clusterin levels are elevated in many different pathological conditions, like apoptosis, hypoxia, or neurodegenerative conditions, and in several diseases, such as diabetes and atherosclerosis, and treatment recurrent cancers, including castrate resistant prostate cancer." (PMID 29200898, 2017). "In addition, no study has investigated the association of CLU rs11136000 polymorphism with diabetes-related MCI." (PMID 27516739, 2016). "ApoJ/CLU has a nearly ubiquitous expression pattern in humantissues and has been implicated in various physiological processes and in manysevere physiological disturbance states including ageing, cancer progression,vascular damage, diabetes, kidney, and neuron degeneration." (PMID 18464919, 2008). "Thus, pancreas-targeted CLU OE causes metabolic deregulation being evident by altered expression of mitochondrial and metabolic genes, along with exaggeration of diabetic phenotypes as manifested by decreased GLU, INS and PYR tolerance in basal conditions or in a model of STZ-induced diabetes." (PMID 33744871, 2021). "Here, we report that glomerular clusterin expression was increased in patients with DN and a mouse model of STZ-induced diabetes." (PMID 32913257, 2020). "The results showed that the variables associated with MCI in T2DM diabetes include old age, low education levels, long duration of diabetes, low HDL-c level, CVD history, and high HbA1c and clusterin levels." (PMID 27516739, 2016). "In vivo findings showed that lack of BRD7 protected against diabetes-induced testicular damage and ferroptosis via increasing Clusterin expression and activating AMPK signaling." (PMID 38992588, 2024). "This suggests that CLU may play an important role in the development of diabetes, but the role and mechanism of CLU in diabetic atherosclerosis have not yet been elucidated." (PMID 40337510, 2025). "Additionally, comparison of the expression level of LAMA2, MLL4, PLXDC2, CD14, CLU, CD99 and SAA2 in sera of healthy volunteers and patients with stroke and pre-diabetes suggests that LAMA2, MLL4 and PLXDC2 have better specificity for (pre-)diabetes than CD14, CLU, CD99 and SAA2." (PMID 33995275, 2021). "Finally, in a streptozotocin (STZ)-mediated diabetes induction model, we observed that STZ treated TgI173, TgI178 Tg animals (pancreas specific CLU OE) had constantly higher GLU levels in relation to control animals, indicating an exaggeration of the STZ-induced diabetic phenotype." (PMID 33744871, 2021). "In our AMI model (in pigs not suffering from atherosclerosis, high cholesterol or diabetes) we could examine clusterin expression in acute myocardial ischemia without any confounding factors." (PMID 32605184, 2020).
diabetes (continued). "Since we found that increased CLU levels in pancreas and liver from the tissue specific CLU Tg mice do not induce premature onset of diabetes but exacerbate INS intolerance, we suggest that pancreas specific CLU upregulation may result in deregulation of the GLU-INS metabolic pathway." (PMID 33744871, 2021).
atherosclerosis (36 papers, 2014 to 2026). A disease characterized by the build-up of fatty material and calcium deposition in the arterial wall resulting in partial or complete occlusion of the arterial lumen. "CLU deficiency has been shown to result in lipid accumulation in the mouse kidney, and CLU has also been suggested to protect against atherosclerosis through its lipid transport function." (PMID 40319306, 2025). "Clusterin expression is also associated with diabetes type II and high cholesterol levels, both being well known risk factors for atherosclerosis and AMI." (PMID 32605184, 2020). "In turn, high clusterin levels have been linked to atherosclerosis." (PMID 36291661, 2022). "Comparison of top-scored IPA canonical analysis showed that atherosclerosis signaling may relate to interactions between CLU and proteins encoded by congenital toxoplasmosis susceptibility genes (TGFβ1, COL2A1, ALOX12, NFκB1)." (PMID 28904337, 2017). "Compared to patients with atherosclerosis alone, diabetic atherosclerosis patients had higher mRNA levels of CLU." (PMID 40337510, 2025). "Clusterin, which is a glycoprotein involved in cellular protection, is found to be elevated in response to vascular injury and atherosclerosis." (PMID 39767589, 2024). "Disturbances in the function of clusterin as a chaperone protein contribute to the development of storage diseases such as amyloidosis, atherosclerosis, Alzheimer's or Creutzfeldt-Jakob disease." (PMID 36071866, 2022). "Many studies have highlighted the involvement of clusterin in all stages of atherosclerosis suggesting its potential role as biomarker of atherosclerosis lesions and CVDs." (PMID 33086718, 2020). "In humans, apoJ (Clusterin) is involved in many diseases related to oxidative stress, including atherosclerosis, neurodegenerative diseases, cancers, inflammatory diseases, and aging." (PMID 32462055, 2020). "Clusterin (CLU) (or Apolipoprotein [Apo] J)levels have been reported to be elevated during the progression ofpostangioplasty restenosis and atherosclerosis." (PMID 30281685, 2018). "First, overexpression of clusterin has been observed in many inflammatory conditions, including human atheromatous atherosclerosis, where it is observed only in vascular smooth muscle cells and stroma of atheromas and not in normal aorta." (PMID 26986213, 2016). "Clusterin is known to accumulate in the artery wall during the development of atherosclerosis and has been localized in the infarcted heart during myocardial infarction." (PMID 24949022, 2014). "In aortic tissue, CLU expression increases with atherosclerosis progression from fatty streaks to advanced lesions while its presence in normal aortas is unobtrusive." (PMID 24758255, 2014). "Clusterin (CLU) /Apolipoprotein J is a protein biosensor of oxidative stress and inflammation, which is upregulated in many pathological processes including atherosclerosis." (PMID 24758255, 2014). "In addition, the analysis revealed that the T allele of CLU rs-9331896 was associated with an increased risk of AD in general, but not with an elevated risk of atherosclerosis-associated disorders such as ischemic cerebrovascular disease, ischemic heart disease, or vascular dementia." (PMID 36291661, 2022). "Clusterin (CLU) is involved in the clearance of misfolded proteins, regulation of apoptosis, inflammation, atherosclerosis, and cancer." (PMID 35517047, 2022). "Similarly, clusterin and CPN1 were selected based on evidence of their roles in cellular protection and tissue remodeling, which are critical in atherosclerosis and CAD." (PMID 39767589, 2024).
dementia (35 papers, 2012 to 2026). Loss of intellectual abilities interfering with an individual's social and occupational functions. "We showed that lower levels of CSF CLU are associated with an increased risk of dementia progression in an extended cohort from the Knight ADRC." (PMID 38687811, 2024). "Some proteins, such as clusterin (CLU) or apolipoprotein J (APOJ), have been found to be associated with dementia, neurological inflammation, and oxidative stress during such AD conditions." (PMID 37873875, 2023). "We, therefore, investigated the diagnostic value of clusterin by quantifying clusterin using an ELISA in plasma from 171 controls, 127 patients with AD, 82 patients with other dementias and 30 patients with depression." (PMID 23209684, 2012). "These may include factors already associated with cognitive dysfunction and dementia in other populations, such as apolipoprotein E, complement receptor 1, clusterin, sortilin-related receptor 1, catechol-O-methyltransferase and BDNF." (PMID 40235626, 2025). "Plasma β amyloid (Aβ), clusterin, and tau are blood biomarkers that have been associated with dementia and stroke, and may be involved in CSVD." (PMID 32588552, 2020). "Clusterin levels have been related to dementia and stroke, but the relation is complex and influenced by several factors." (PMID 32588552, 2020). "The role of human kallikrein 6, clusterin and adiponectin as potential blood biomarkers of dementia." (PMID 31969813, 2019). "In summary, we have shown high differential clusterin protein expression in some cerebrovascular disorders related to dementia." (PMID 25940137, 2016). "In our study, plasma clusterin was significantly elevated in depressed subject compared to controls and several dementias, adding to the evidence of involvement of inflammation in depression." (PMID 23209684, 2012). "In particular, Apolipoprotein J (ApoJ or clusterin) has been proposed as a biomarker of the disease at the pre-dementia stage." (PMID 22701550, 2012). "Among the proteins, APOE, CLU, CHL1, SLC1A3, RAB7A, and CST3 were related to the protein aggregation of misfolded proteins—causative agents and symptomatic of neurodegenerative diseases—such as α-synuclein in PD, and amyloid-β and tau in dementia." (PMID 36797805, 2023). "This suggests that CLU hypomethylation is related to limited types of dementia." (PMID 32991610, 2020). "Because concomitant proteinopathies are frequently found in dementias, clusterin in combination with α-synuclein could be especially useful in identifying those patients most likely to benefit from therapies targeting intraneuronal α-synuclein." (PMID 32273329, 2020). "We found that aMCI patients showed an increased trend in clusterin levels and trended toward a decreasing performance in cognitive tests, changes that are identified as potential candidates for early events in the pre-dementia stages." (PMID 26503441, 2015). "We observed similar plasma clusterin levels in controls, AD patients and patients with other dementias, suggesting that plasma clusterin levels have no diagnostic value for AD." (PMID 23209684, 2012). "Notably, while biomarker studies have implicated clusterin as a late‐onset sporadic AD biomarker, dementia in DS is an early onset genetically determined type of AD; no published studies address clusterin levels in familial AD." (PMID 36149090, 2023). "To clarify how specific the methylation changes detected are in dementia, we examined the methylation levels of APOE and CLU in blood samples of control, AD, dementia with Lewy bodies (DLB), vascular dementia (VaD), and frontotemporal dementia (FTD)." (PMID 32991610, 2020). "One of these, clusterin (Gene symbol CLU), was previously reported to be reduced in patients with HIV associated dementia relative to non-demented control samples." (PMID 22433316, 2012). "Moreover, CSF clusterin was also associated with T-tau in both the MCI and dementia subgroups, but not the SCD group." (PMID 30791945, 2019).